TOM1L1 (target of myb1 like 1 membrane trafficking protein)
Description:
Probable adapter protein involved in signaling pathways. Interacts with the SH2 and SH3 domains of various signaling proteins when it is phosphorylated. May promote FYN activation, possibly by disrupting intramolecular SH3-dependent interactions (By similarity).
Synonyms: SRCASM
Tractability: Antibody: UniProt places it where antibodies can reach, with high confidence. PROTAC: ubiquitination databases record sites on it; its protein half-life has been measured.
Gene: Protein-coding gene on chromosome 17 (54,899,387 to 54,963,841, forward strand). Ensembl gene ENSG00000141198.
Subcellular location: Golgi apparatus, Golgi stack; Endosome membrane; Cytoplasm; Membrane
Gene Ontology:
Molecular function: clathrin binding; protein binding; protein kinase binding; ubiquitin binding; phosphatidylinositol binding; protein kinase activator activity
Biological process: activation of protein kinase activity; negative regulation of mitotic nuclear division; positive regulation of protein autophosphorylation; regulation of DNA biosynthetic process; signal transduction; ubiquitin-dependent protein catabolic process via the multivesicular body sorting pathway
Cellular component: cytoplasm; cytosol; endosome; extracellular exosome; lysosome; membrane; endosome membrane; Golgi stack
Genetic constraint (gnomAD): Loss-of-function variants: 47 observed, 45.74 expected, observed/expected ratio (o/e) 1.03, 90% interval 0.81 to 1.31. The upper end of that interval is the gene's LOEUF score, 1.31, which puts it in group 5 of 6, group 1 being the genes least tolerant of losing a copy. Missense variants: 418 observed, 478.59 expected, observed/expected ratio (o/e) 0.87, 90% interval 0.81 to 0.95. Synonymous variants: 147 observed, 169.07 expected, observed/expected ratio (o/e) 0.87, 90% interval 0.76 to 1.
Homologues: Orthologues: chimpanzee TOM1L1 (99% identical), macaque TOM1L1 (96% identical), dog TOM1L1 (85% identical), pig TOM1L1 (85% identical), rabbit TOM1L1 (84% identical), mouse Tom1l1 (80% identical), guinea pig TOM1L1 (79% identical), rat Tom1l1 (67% identical), tropical clawed frog tom1l1 (41% identical), Caenorhabditis elegans C07A12.7 (25% identical), Drosophila melanogaster CG3529 (25% identical), Drosophila melanogaster Gga (18% identical), and 4 more. Paralogues in human: TOM1 (33% identical), TOM1L2 (33% identical), GGA1 (20% identical), GGA3 (19% identical), GGA2 (19% identical), STAM2 (18% identical), HGS (17% identical), STAM (16% identical), WDFY1 (9% identical), WDFY2 (8% identical).
Diseases named in the same sentence as TOM1L1 in open-access papers:
TOM1L1 is named in the same sentence as 15 diseases in open-access papers, as found by Europe PMC text mining. Sharing a sentence is not in itself a finding about the gene and the disease. The quoted sentences say what the papers report.
breast carcinoma (10 papers, 2014 to 2025). "TOM1L1 has been implicated in the progression of several cancers, such as breast cancer and clear cell renal cell carcinoma." (PMID 40090864, 2025). "Previous studies have identified TOM1L1 as a gene associated with m6A-SNPs in breast cancer." (PMID 40303916, 2025). "Studies have shown that TOM1L1 is associated with breast cancer." (PMID 34151731, 2021). "And TOM1L1 was able to promote ERBB2-induced breast cancer cell invasion by driving membrane delivery of membrane-type 1 matrix metalloprotease (MT1-MMP)." (PMID 40303916, 2025). "ERBB2-induced breast cancer cell invasion has been documented to be caused by the TOM1L1-derived membrane delivery of MT1-MMP, and ERBB2 and TOM1L1 are frequently coamplified in the breast." (PMID 34917619, 2021). "Conversely, our study demonstrates a pro-tumoural function for the GAT-containing trafficking protein TOM1L1 in human breast cancer and shows that its pro-oncogenic activity is induced by gene co-amplification with the ERRB2 oncogene." (PMID 26899482, 2016). "We next investigated TOM1L1 role in breast cancer by manipulating its expression level in ERBB2+/ER+/TOM1L1− SKBR3 cells (by overexpression) and in ERBB2+/ER+/TOM1L1+ BT-474 cells (by short interfering RNA (shRNA)-mediated silencing)." (PMID 26899482, 2016). "MYB1-like protein 1 (TOM1L1) is relevant to bone metastasis in breast cancer." (PMID 35839032, 2022). "Moreover, in breast cancer samples, TOM1L1 protein expression, assessed by immunohistochemistry (IHC), was significantly associated with both ER (P=0.027) and ERBB2 (P=0.001) expression." (PMID 26899482, 2016). "This study confirms the role of m6A-SNPs in influencing endocrine therapy resistance in ER+ breast cancer, highlighting how modifications mediated by specific SNPs, particularly in FILIP1L and TOM1L1, impact key regulatory pathways and cellular metabolism." (PMID 40303916, 2025). "Specifically, TOM1L1 and ESR1 were highly expressed, but MAFF, TNS1, EFEMP2, and TRIM31 were significantly downregulated in breast cancer." (PMID 34151731, 2021). "Of the candidate genes in the region, both COX11 and TOM1L1 are highly expressed in both the HMEC and MCF7 breast cancer cell lines, while STXBP4 shows much lower expression (detected by RNAseq in TCGA)." (PMID 27600471, 2016). "Deletion of the GAT domain (ΔGAT mutant) abolished TOM1L1 pro-invasive activity in SKBR3 cells and in HCC-1954 cells (another ERBB2+/ER+/TOM1L1− breast cancer cell line)." (PMID 26899482, 2016). "In breast cancer, ER-regulated genes including FGFR1 and IRS1, and ERK1-regulating genes including IRF6 and TOM1L1, were aberrantly methylated." (PMID 24842468, 2014). "In ER+ breast cancer, the modulation of the PI3K-Akt and Wnt signaling pathways by m6A-SNPs related genes like FILIP1L and TOM1L1 is particularly compelling, given the established role of these pathways in promoting estrogen receptor signaling and cellular proliferation." (PMID 40303916, 2025). "Although TOM1L1 regulates the oncoprotein ERBB2-driven cell invasion with metastatic phenotypes in breast cancer, there is no available information on the role of this gene in CC." (PMID 33023042, 2020). "Modulation of TOM1L1 expression did not have any effect on growth and migration of these breast cancer cells." (PMID 26899482, 2016). "Collectively, these results show that TOM1L1 is an important element of an ERBB2-driven proteolytic invasive programme and that TOM1L1 amplification potentially enhances the metastatic progression of ERBB2-positive breast cancers." (PMID 26899482, 2016). "Only six genes were differentially expressed between controls and breast cancer cases in GEO datasets (GSE15852, GSE115144, and GSE109169), and the SNPs rs4829 and rs9610915 were located next to the m6A modification sites in the 3ʹUTRs of TOM1L1 and MAFF, respectively." (PMID 34151731, 2021).
breast carcinoma (continued). "Thus, TOM1L1 is an important element of an ERBB2-driven proteolytic invasive programme and TOM1L1 amplification potentially enhances the metastatic progression of ERBB2-positive breast cancers." (PMID 26899482, 2016). "Finally, we checked whether this TOM1L1 invasive role was conserved in breast tumour cells by overexpressing TOM1L1 in the ERBB2- and TOM1L1-negative breast cancer cell line MDA-MB-231." (PMID 26899482, 2016).
glioblastoma (2 papers, 2022 to 2025). The most malignant astrocytic tumor (WHO grade IV). "To investigate the functional role of PTM‐related prognostic genes in glioblastoma, we conducted a series of experiments targeting TOM1L1, a gene believed to impact the malignancy of tumors potentially." (PMID 40090864, 2025). "First, bioinformatic analysis of the Cancer Cell Line Encyclopedia (CCLE) revealed these cell lines among the top TOM1L1‐expressing glioblastoma models, ensuring physiological relevance for functional studies." (PMID 40090864, 2025).
glioma (2 papers, 2022 to 2025). A benign or malignant brain and spinal cord tumor that arises from glial cells (astrocytes, oligodendrocytes, ependymal cells). "Among the genes included in the model, TOM1L1 (Target of Myb1 Like 1 Membrane Trafficking Protein) was selected for in vitro experimental validation to assess its role in glioma progression." (PMID 40090864, 2025). "The prognostic model, comprising DEGs such as TOM1L1, demonstrated high predictive accuracy (c‐index = 0.867)—the scores derived from the model strongly correlated with glioma progression indicators." (PMID 40090864, 2025). "While TUBA1C and FBXO17 have been extensively studied in glioma and are known to promote tumor progression, TOM1L1's role in glioma remains underexplored, particularly in the context of PTM‐mediated mechanisms." (PMID 40090864, 2025). "While TOM1L1 (Target of Myb1‐Like 1) has been implicated in endosomal trafficking and immune regulation, its role in PTM‐mediated glioma progression remains entirely unexplored." (PMID 40090864, 2025). "The suppression of TOM1L1 significantly diminished malignant behaviors, indicating its role in promoting the aggressive phenotype of glioma." (PMID 40090864, 2025). "Among these genes, TOM1L1 emerged as a critical driver of glioma progression." (PMID 40090864, 2025). "Understanding how TOM1L1 influences PTM processes like phosphorylation or ubiquitination could provide valuable insights into its role in promoting glioma progression and potentially identify new therapeutic targets." (PMID 40090864, 2025). "Therefore, the pro‐tumorigenic mechanisms of TOM1L1 in glioma, particularly concerning PTM pathways, warrant further investigation." (PMID 40090864, 2025). "This interaction may explain TOM1L1's impact on glioma cell proliferation, migration, and invasion." (PMID 40090864, 2025). "In vitro experiments revealed that TOM1L1 facilitates malignant progression by modulating PTM pathways, confirming its functional role in glioma." (PMID 40090864, 2025). "However, the precise PTM‐related targets and pathways regulated by TOM1L1 in glioma remain unclear." (PMID 40090864, 2025).
bladder cancer (1 paper, 2021). "Other studies have also found that TOM1L1 is related to colorectal cancer and is highly expressed in bladder cancer." (PMID 34917619, 2021).
breast tumours (1 paper, 2016). "Analysis of a set of 402 breast tumours showed that TOM1L1 was the most frequently co-amplified gene with ERBB2 in the 17q22-q23 region." (PMID 26899482, 2016).
cutaneous squamous cell carcinoma (1 paper, 2023). "In cutaneous squamous cell carcinoma, TOM1L1 expression levels are decreased and related to precursor lesions." (PMID 36611973, 2023).
epilepsy (1 paper, 2025). A brain disorder characterized by episodes of abnormally increased neuronal discharge resulting in transient episodes of sensory or motor neurological dysfunction, or psychic dysfunction. "In epilepsy, mapping our m6A-associated genes (e.g., PARP1, NBL1, RPL14) to their proteomic counterparts identified causal links to proteins such as ST6GALNAC5, CTNNA2, and TOM1L1, highlighting specific m6A-driven regulatory cascades at the protein level." (PMID 40624693, 2025).
kidney cancer (1 paper, 2023). Primary or metastatic malignant neoplasm involving the kidney. "However, there have been no related studies on TOM1L1 in kidney cancer." (PMID 36611973, 2023).
parasitic infection (1 paper, 2020). "Genetic variants of interest identified in several immune related genes for all the antibody response and parasitic infection traits: IBDV (TOLLIP, ANGPTL5, BCL9, THEMIS2), MDV (GRM7), SG (MAP3K21), Eimeria (TOM1L1), and cestodes (TNFAIP1, ATG9A, NOS2)." (PMID 33193617, 2020).
toxicity (1 paper, 2025). The degree to which an agent can damage an organism. "It is noteworthy that all target antigens (ROCK2, TOM1L1, NMD3, CPT1A, and MIT3) are expressed in normal skin according to the Human Protein Atlas, consistent with a possible relationship between autoantibodies and skin toxicity." (PMID 40828987, 2025).
tumor (7 papers, 2016 to 2025). "The dynamic regulation of FILIP1L and TOM1L1 along the developmental trajectory of tumor cells from sensitivity to resistance provides insights into the molecular complexity of therapy resistance." (PMID 40303916, 2025). "In the ICGC dataset, CFB and PPP1R18 were significantly upregulated in tumor samples, whereas TOM1L1 was significantly downregulated in tumor samples." (PMID 36611973, 2023). "In the three GEO datasets, the expression of CFB and PPP1R18 was significantly higher in tumor samples, whereas that of TOM1L1 was significantly lower." (PMID 36611973, 2023). "Compared to nondistant metastatic ccRCC tissues and normal tissues, the expression patterns of CFB and PPP1R18 were significantly higher in distant metastatic ccRCC samples and tumor samples, whereas the expression of TOM1L1 was significantly lower." (PMID 36611973, 2023). "The phosphorylation event promotes GAT-dependent association of TOM1L1 with the sorting protein TOLLIP and trafficking of the metalloprotease MT1-MMP from endocytic compartments to invadopodia for tumour cell invasion." (PMID 26899482, 2016). "Here the authors report that ERBB2 induces indirect phosphorylation of TOM1L1 that promotes trafficking of the metalloprotease MT1-MMP to invadopodia, which leads to tumour cell invasion." (PMID 26899482, 2016). "Here we report that TOM1L1 is co-amplified with ERBB2 and defines a subgroup of HER2+/ER+ tumours with early metastatic relapse." (PMID 26899482, 2016).
cancer (6 papers, 2016 to 2025). A tumor composed of atypical neoplastic, often pleomorphic cells that invade other tissues. "On the other hand, a new set of potential biomarkers (NCKAP1, TNFRSF12A, LAMB2, FKBP9, PFN2, TOM1L1) and expression rules for the identification of different cancers at the transcriptome level were discovered." (PMID 34917619, 2021). "In conclusion, we show that ERBB2 exploits the trafficking function of TOM1L1 to promote cancer cell invasion." (PMID 26899482, 2016). "Among the 19 cancer types, PPP1R18/KIAA1949 (p = 2.98 × 10−32) and TOM1L1 (p = 3.87 × 10−30) exhibited the highest specificity for KIRC/ccRCC, and CFB also presented excellent specificity for KIRC/ccRCC (p = 3.76 × 10−13)." (PMID 36611973, 2023). "Although there still no studies revealed the roles of FILIP1L and TOM1L1 in m6A modification, their functions in cancer have been preliminarily described." (PMID 40303916, 2025). "It is not known why TOM1L1 is not tyrosine-phosphorylated in ERBB2-positive cancer cells." (PMID 26899482, 2016).
TOM1L1 also shares sentences with these, for which no sentence is quoted: clear cell renal cell carcinoma (1 paper); colorectal cancer (1); low grade glioma (1).